ICAM1 (intercellular adhesion molecule 1)
Diseases named in the same sentence as ICAM1 in open-access papers (continued):
Sharing a sentence is not in itself a finding about the gene and the disease.
multiple sclerosis (18 papers, 2008 to 2024). A progressive autoimmune disorder affecting the central nervous system resulting in demyelination. "As far as we know, two prior meta-analyses from 2000 and 2003 evaluated the association of ICAM1 rs5498 with the risk of multiple sclerosis; however, different conclusions were obtained." (PMID 30473535, 2018). "Fourth, we only investigated the impact of the ICAM1 rs5498 polymorphism in the susceptibility to multiple sclerosis." (PMID 30473535, 2018). "Herein, we aimed to comprehensively estimate the possible genetic impacts of the rs5498 polymorphism of the ICAM1 (intercellular adhesion molecule 1) gene on the susceptibility to multiple sclerosis." (PMID 30473535, 2018). "In the present study, we included currently published evidence to comprehensively evaluate the influence of the rs5498 polymorphism within the ICAM1 (intercellular adhesion molecule 1) gene on the genetic risk of multiple sclerosis." (PMID 30473535, 2018). "ICAM-1 is aberrantly expressed by astrocytes in CNS pathologies, such as multiple sclerosis, experimental allergic encephalomyelitis and Alzheimer’s disease, suggesting a possible role for ICAM-1 in these disorders." (PMID 36980289, 2023). "ICAM-1-/- or mutant mice exhibited less T cell infiltration in the CNS and less clinical disability in a mouse model of multiple sclerosis." (PMID 37644514, 2023). "Increased expression of ICAM1 has been demonstrated in endothelial cells, microglia, and astrocytes in patients with multiple sclerosis (Carrithers, Visintin, Kang, & Janeway, 2000; Mycko, Kwinkowski, Tronczynska, Szymanska, & Selmaj, 1998)." (PMID 31464097, 2019). "For example, ICAM1 is targeted by natalizumab, which is approved for treatment of multiple sclerosis." (PMID 28245581, 2017). "In EAE, as well as in multiple sclerosis (MS), ICAM-1, VCAM-1, and ALCAM are upregulated." (PMID 32753493, 2020). "For example, the ‘G/G’ genotype of the ICAM1 rs5498 polymorphism was reportedly associated with a reduced risk of multiple sclerosis patients in Poland rather than Finland." (PMID 30473535, 2018). "In conclusion, we incorporated the current data for an updated pooling analysis, which indicated that the ICAM1 rs5498 polymorphism is not linked to the risk of multiple sclerosis in Caucasian and Asian populations." (PMID 30473535, 2018). "In 2000, Killestein, J. enrolled three case–control studies to conduct the first meta-analysis by the Mantel–Haenszel method and did not detect the genetic role of ICAM1 rs5498 polymorphism in the risk of multiple sclerosis." (PMID 30473535, 2018). "Hence, our data failed to support a strong connection between ICAM1 rs5498 polymorphism and the susceptibility to multiple sclerosis, which is in line with the conclusion of prior pooling analysis." (PMID 30473535, 2018). "Additionally, the ICAM1 rs5498 polymorphism was not related to the multiple sclerosis risk in Dutch or Iranian populations or in the Han nationality of Henan, China." (PMID 30473535, 2018). "As a consequence, ICAM1 rs5498 may not be associated with the risk of multiple sclerosis in Caucasian or Asian populations." (PMID 30473535, 2018). "IL‐1 plays a vital role in the pathophysiology of multiple sclerosis (MS), and inhibition of IL‐1 signaling in the BBB markedly ameliorates the severity of MS by downregulating the expression of ICAM‐1 and other proinflammatory mediators." (PMID 34156153, 2021). "ICAM1 expression is upregulated at the BBB under inflammatory conditions and ischemia, and in CNS inflammatory diseases such as multiple sclerosis and experimental allergic encephalitis." (PMID 32585920, 2020). "Thus, we conclude that ICAM1 rs5498 may not be related to the risk of multiple sclerosis in Caucasian or Asian populations, which still merits further research." (PMID 30473535, 2018).
multiple sclerosis (continued). "For example, in the serum of Cx3cr1−/− mice, the levels of ICAM1 were reduced and those of CXCL12 were elevated, oppositely to the changes observed in these molecules during an inflammatory condition, such as multiple sclerosis." (PMID 29251592, 2017). "Furthermore the beneficial effects of WIN in a chronic model of multiple sclerosis were partially mediated by down-regulating adhesion molecules VCAM-1 and ICAM-1." (PMID 27158245, 2016). "In autoimmune demyelinating diseases, an ICAM-1 isoform lacking D4 in the mouse may drive pathogenesis and may be a novel therapeutic target for the treatment of multiple sclerosis (MS)." (PMID 38391953, 2024). "Two of these, ICAM1 and ATM, are existing drug targets used in the treatment of multiple sclerosis, fatigue, orthostatic hypotension and osteoarthritis (natalizumab, caffeine and hyaluronic acid, respectively) and may provide potential targets for repositioning." (PMID 31092410, 2019).
breast tumor (17 papers, 2012 to 2025). "Several cell adhesion molecules such as ICAM 1, laminin and fibronectin have been associated with the invasive process, growth, and metastasis of breast tumors." (PMID 29244827, 2017). "Recent study revealed that ICAM-1 expression was associated with a more aggressive breast tumor phenotype." (PMID 23874773, 2013). "Consistent with these in vivo results, TENs isolated from E0771 breast tumor-bearing mice could also kill control E0771 cells more readily than their ICAM-1-deficient E0771 cell counterparts in vitro." (PMID 35911772, 2022). "Indeed, high levels of ICAM1 mRNA expression in breast tumors were associated with an unfavorable distant metastasis-free survival (DMFS) as well as disease-specific survival (DSS) (ICAM1 alone and along with the stemness signature genes)." (PMID 34381029, 2021). "(2021) have recently studied the role of ICAM in trans-endothelial migration in breast cancer and also assessed the therapeutic efficacy of anti-ICAM1 neutralizing antibody on breast tumor cell aggregation and trans-endothelial migration." (PMID 37056346, 2023). "To study the role of ICAM-1 in breast tumor progression and metastasis in a murine model, we deleted it from E0771 cells using CRISPR/Cas9 targeting." (PMID 35911772, 2022). "It has been shown that breast tumor express ICAM-1 and interacts with integrin β2 on neutrophil granulocytes." (PMID 36386163, 2022). "Breast tumors and their derived circulating cancer cells express the leukocyte β2 integrin ligand Intercellular adhesion molecule 1 (ICAM-1)." (PMID 35911772, 2022). "In breast tumor cells, ICAM1 promotes many pathways and signature genes related to stemness and the cell cycle, including CDK6 as one of the essential targets." (PMID 34381029, 2021). "The anti-ICAM1 antibody also significantly blocked TEM of L2G-labeled breast tumor cells in a transwell insert pre-coated with confluent HUVECs." (PMID 34381029, 2021). "We next assessed the therapeutic effects of an anti-ICAM1 neutralizing antibody on breast tumor cell aggregation and TEM." (PMID 34381029, 2021). "Our results show for the first time that ICAM-1 is up-regulated in breast tumor cells in response to AngII treatment." (PMID 22536420, 2012). "Clinical data also showed high levels of ICAM1 mRNA expression in breast tumors which might mediate distant metastasis." (PMID 37056346, 2023). "The primary breast tumors of either control or ICAM-1 KO OVA-expressing E0771 cells were implanted in syngeneic mice; 3 days later, OT-I CTLs were i.v.-injected into these mice, and the tumor size was monitored from day 12 to day 16 postinitial tumor implantation." (PMID 35911772, 2022). "Next, to clarify whether our observations were exclusive of the B16-VEGFC tumor model, we performed the ICAM-1 blocking experiments in Her2/Neu transgenic mice bearing spontaneous breast tumors." (PMID 30258446, 2018). "Through down-regulating E-Cadherin expression and up-regulating ICAM-1 and Integrin β1 expressions, miR-19b could obviously promote breast tumor growth and facilitate cancer metastasis." (PMID 28969074, 2017). "Breast tumor cells lack β2 integrins, which are a ligand for ICAM-1 on the endothelium." (PMID 25275457, 2014). "While CD44+ breast tumor-initiating cells can contribute to CTC cluster formation and lung metastasis of TNBC8, our work suggests that ICAM1 and CD44 independently direct cancer metastasis." (PMID 34381029, 2021). "Additionally, miR-19b could obviously promote breast tumor growth in mouse models and affect the expressions of cell adhesion molecules (including E-Cadherin, ICAM-1 and Integrin β1) by down-regulating E-Cadherin expression and up-regulating ICAM-1 and Integrin β1 expressions in vitro and in vivo." (PMID 28969074, 2017). "In breast tumor D3H2LN cells, AngII upregulates MMP-2 / MMP-9 and ICAM1, which are involved in cell adhesion, migration, and invasion." (PMID 29179450, 2017).
breast tumor (continued). "Modulation of genes related with invasion, metastasis and chemoresistance (ICAM-1, CXCL1, TNFAIP3, IL8) were confirmed in additional doxorubicin-treated cell lines and fresh primary human breast tumors." (PMID 24344116, 2014). "Importantly, as observed with small E0771 breast tumors, the growth of the large tumors and the main leukocyte composition of their TME were unaffected by E0771 ICAM-1 expression." (PMID 35911772, 2022). "Nevertheless, we could not detect the circulating RFP+ tumor cells (CTCs) of either control or ICAM-1 KO E0771 cell tumors in the circulation following the resection of the respective primary breast tumors (data not shown)." (PMID 35911772, 2022). "Thus, the antitumor immune response experienced by E0771 cells inside a primary breast tumor elicited by E0771 cells implanted in a distal site does not depend on ICAM-1 expression on the tumor target." (PMID 35911772, 2022). "It was demonstrated that high-density lipoprotein (HDL)-mediated transfer of miR-223 inhibited intercellular adhesion molecule 1 (ICAM1) expression in endothelial cells and we demonstrated that breast tumor-derived non-exosomal LDL-miR-375 was taken up by tumor-associated macrophages via CD36." (PMID 32276464, 2020). "Collectively, these results suggest that the killing of E0771 cells within primary breast tumors by either endogenous or exogenous (i.e., OVA-specific) Ag-specific CTLs does not require ICAM-1 expression on the tumor cell targets." (PMID 35911772, 2022).
dementia (17 papers, 2013 to 2025). Loss of intellectual abilities interfering with an individual's social and occupational functions. "A recent longitudinal study found elevated cerebrospinal fluid levels of ICAM-1, along with other cerebrovascular-associated proteins, in the preclinical, prodromal and dementia stages of AD." (PMID 38178159, 2024). "ICAM-1 level was higher in preclinical, prodromal, and dementia stages of AD and linked with CDR-SB scores." (PMID 35769604, 2022). "Studies have shown that CSF levels of VCAM-1 and ICAM-1 are increased in the preclinical, prodromal, and dementia stages of AD, similar to YKL-40." (PMID 36142483, 2022). "Another protein that stands out is ICAM-1 of which increased levels are present in the CSF of preclinical, prodromal and dementia AD stages." (PMID 34425919, 2021). "Finally, higher levels of CSF ICAM-1 increased the risk of developing AD dementia in patients without dementia." (PMID 31824303, 2019). "Finally, higher levels of CSF YKL-40, ICAM-1, and Flt-1 increased risk of development of AD dementia in patients without dementia." (PMID 30054439, 2018). "CSF levels of YKL-40, ICAM-1, VCAM-1, IL-15, and Flt-1 were increased during the preclinical, prodromal, and dementia stages of AD." (PMID 30054439, 2018). "Phenotypically, NK cells from MS donors displayed a more migratory profile than those from control and dementia cases: higher expression of CD49d (integrin alpha-4), CD54 (ICAM1 or intercellular adhesion molecule 1), and CD31 (PECAM1 or platelet endothelial cell adhesion molecule)." (PMID 35536009, 2022). "In the present study, using a large cohort of well-characterized patients, we show increased levels of ICAM-1, VCAM-1, IL-15, and Flt-1in AD at the preclinical, prodromal, and dementia stage, indicating that neuroinflammatory pathways are activated early in the disease course." (PMID 30054439, 2018). "Upregulation of adhesion molecules such as ICAM-1 (intercellular adhesion molecule 1) and VCAM-1 in astrocytes is required for monocyte-astrocyte interaction which increases infiltration of monocytes into the CNS observed in the patients with HIV-1 dementia." (PMID 24455696, 2013). "CSF markers of endothelial injury, such as VEGF‐A, ICAM‐1, and VCAM‐1 were associated with elevated Qalb and are also raised in other dementia‐associated diseases, indicating that these changes may not be AD specific." (PMID 41319164, 2025). "In the dementia group, CSF ApoA1 levels correlated positively with CSF ICAM1 and VACM1 levels [correlation range 0.55 to 0.62, all p < 0.001], while a negative correlation was observed between plasma ApoA1 and CSF ICAM1 and VCAM1, but this correlation was not significant." (PMID 36927447, 2023).
influenza (17 papers, 2016 to 2025). An acute viral infection of the respiratory tract, occurring in isolated cases, in epidemics, or in pandemics; it is caused by serologically different strains of viruses (influenzaviruses) designated A, B, and C, has a 3-day incubation period, and usually lasts for 3 to 10 days. "Since PR8 expands mainly in epithelial cells, these results indicate that loss of epithelial ICAMs doesn’t impair influenza infection, contrasting a previous report on ICAM-1 dependence of this infection in airway derived epithelial cells as assessed in vitro." (PMID 36895258, 2022). "Strikingly, the number of polyclonal TRM cells generated following X31 influenza infection was similar in ICAM-1/2-/- and WT mice." (PMID 36895258, 2022). "We therefore next followed the fate of polyclonal effector CD8+ T cells residing in the ICAM-1/2-/- lungs 40 days post primary infection with the influenza H3N2 subtype A/HK/X31 strain." (PMID 36895258, 2022). "Strikingly, significantly elevated numbers of monoclonal OVA specific Tfh cells were generated from adoptively transferred naïve CD4+ OT-II T cells inside MedLNs of influenza infected ICAM-1/2-/- mice." (PMID 36895258, 2022). "Although vWF and ICAM-1 are upregulated during influenza infection, platelet adhesion to influenza-infected endothelial cells is primarily mediated by other molecules, such as endothelial fibronectin and platelet α5β1." (PMID 35419008, 2022). "Strikingly, however, similar numbers of early OT-II T follicular helper (Tfh) cells were recovered inside the MedLNs of both influenza infected WT and ICAM-1/2-/- mice at later time points post infection." (PMID 36895258, 2022). "Azithromycin and other macrolides, like bafilomycin A1, erythromycin, and clarithromycin were found to impede the making of IL-1β, IL-6, IL-8, TNF-α, and ICAM-1 in influenza- and RV-modeled infections." (PMID 33937285, 2021). "Notably, the numbers of Vβ8.3+/CD8+ effectors recovered in total lung suspensions of I.N. infected lungs subjected to a secondary I.T. homosubtypic PR8 influenza challenge were reduced in ICAM-1/2-/- lungs compared with WT lungs." (PMID 36895258, 2022). "Thus, ICAM-1/2-/- mice not only normally cleared the PR8 influenza introduced via different routes, but also mounted long lasting memory responses against a secondary infection with a lethal dose of a homosubtypic influenza virus challenge." (PMID 36895258, 2022). "Consequently, the ICAM-1/2-/- influenza specific plasmablasts, produced normal serum levels of anti-PR8 IgGs after both primary infection and secondary challenge." (PMID 36895258, 2022). "Since B-2 B cells undergo isotype switching and affinity maturation depending on helper viral antigen specific CD4+ T cells, we next followed how influenza antigen specific CD4+ T cells accumulate inside the lung draining MedLNs of virus infected ICAM-1/2-/- mice." (PMID 36895258, 2022). "Strikingly, however, viral Ag dependent proliferation and differentiation of naïve CD4+ T cells into effector Tfh cells took place normally and coincided with the appearance of hyperactive cDC2 subsets which accumulated in ICAM-1/2-/- MedLNs of influenza-infected mice." (PMID 36895258, 2022). "Although initial homing of these lymphocytes into lung draining lymph nodes is defective, specific cDC subsets in ICAM-1/2-/- mice appear hyperactivated and thereby compensate for the initially reduced accumulation of T and B cells in the lymph nodes of influenza-infected mice." (PMID 36895258, 2022). "Furthermore, B-2 lymphocytes entering ICAM-1/2-/- LNs combated the primary influenza infection as efficiently as in WT MedLNs, suggesting normal interaction of these lymphocytes with FDCs, the key antigen presenting cells that comprise the B follicles." (PMID 36895258, 2022).